CA2 (carbonic anhydrase 2)
Diseases named in the same sentence as CA2 in open-access papers (continued):
Sharing a sentence is not in itself a finding about the gene and the disease.
neurodevelopmental disorder (2 papers, 2023 to 2024). A behavioral and cognitive disorder with onset during the developmental period that involves impaired or aberrant development of intellectual, motor, or social functions. "Additionally, MR, which is implicated in some social deficits that are characteristic of neurodevelopmental disorders, is enriched in both mouse and human CA2, and genetic deletion of MR in mice impairs social behavior." (PMID 38405991, 2024).
neurological diseases (2 papers, 2017 to 2025). "Calpain is a Ca2+-dependent thiol protease linked mechanistically to the axonal degeneration in neurological diseases." (PMID 28912677, 2017).
CA2 also shares sentences with these, for which no sentence is quoted: autoimmune pancreatitis (8 papers); Sjögren’s syndrome (5); altitude sickness (4); autoimmune disease (4); distal renal tubular acidosis (4); Autoimmunity (3); autosomal recessive osteopetrosis (3); bipolar disorder (3); bladder cancer (3); Cerebral calcification (3); dilated cardiomyopathy (3); medulloblastoma (3); non-small cell lung carcinoma (3); Obesity (3); retinal disorder (3); autism (2); autoimmune retinopathies (2); calcification (2); cancer-associated retinopathy (2); colitis (2); colorectal tumors (2); Ewing sarcoma (2); Hyperglycemia (2); Hypokalemia (2); immune diseases (2); iron deficiency (2); macular edema (2); meningioma (2); metabolic disease (2); myopathy (2).
A further 112 diseases each share a sentence with CA2 in 2 papers or fewer.